GAS6 (growth arrest specific 6)
Diseases named in the same sentence as GAS6 in open-access papers (continued):
Sharing a sentence is not in itself a finding about the gene and the disease.
tumor (continued). "Similarly in our study Gas6 expression in human tumor samples was mainly found in a subpopulation of CD68+ macrophages." (PMID 27486820, 2016). "Moreover, KRASG12D achieves a unique signaling output (e.g., production of ECM, IGF1, and GAS6) via stromal cells that is distinct from that produced by tumor cell KRASG12D alone." (PMID 27087446, 2016). "These dormant disseminated tumor cells (DTCs) may reside in close proximity to osteoblasts, while expressing high levels of Axl, one of the tyrosine kinase receptors for growth arrest specific 6 (Gas6)." (PMID 27819283, 2016). "Further evidence that targeting Gas6 may have therapeutic implications have emerged from recent studies showing an anti-tumor and anti-metastatic role of low—dose warfarin administration." (PMID 27916840, 2016). "In addition to tumor cells, the vasculature, tumor-infiltrating leukocytes, and bone marrow progenitor cells are biologically relevant sources of GAS6 in the tumor microenvironment." (PMID 27834845, 2016). "Murine CT26 tumor cell line displayed even lower expression of Gas6." (PMID 27486820, 2016). "Together, these studies indicated that GAS6/AXL signaling might play an important role in the regulation of tumor growth." (PMID 27834845, 2016). "Additionally, forced over expression of Gas6 in vivo shortened survival time, and conversely, pharmacologic inhibition of Gas6 by blocking y-carboxylation, which is necessary for Gas6 activity, led to decreased tumor burden and prolonged survival." (PMID 27834816, 2016). "In contrast to the preclinical findings in human CRC Gas6 is also expressed to a low level in several different CRC tumor cells in vitro, independent of their origin and mutational status." (PMID 27486820, 2016). "Likewise, stromal cells in the bone marrow upregulate Gas6 when multiple myeloma or metastatic prostate tumor cells are present, positively impacting the malignancy of these tumor cells." (PMID 27775650, 2016). "We found higher Gas6 expression in OSCC tumor tissue, but whether the higher serum Gas6 level is attributable to Gas6 overexpression in OSCC tumor tissue also needs further exploration." (PMID 26207647, 2015). "The presence of Gas6 in HGEOC ascites and in the conditioned media of several EOC cell lines suggests that Gas6, released from the EOCs MCAs or by the cells of the immune system, acts like a fuel to favor tumor invasion and the establishment of secondary lesions." (PMID 26356564, 2015). "Neither AXL nor GAS6 were associated with age, sex, tumour primary location, tumour depth and presence of distant metastasis at initial diagnosis (p > 0.05; data not shown)." (PMID 25966280, 2015). "For example, Gas6/Axl signaling may activate the expression of metalloperoteinase-9 to facilitate tumor invasion through the coordination of ERK signaling, NF-kB and Brg-1 activation." (PMID 26207647, 2015). "Additionally, Axl and Gas6 are coexpressed in tumor vessels, implying a role in neovascularization or angiogenesis." (PMID 25344858, 2014). "However, unlike the pro-proliferative properties of Axl in other cancers, Gas6/Axl signaling in this cellular context leads to tumor cell dormancy and evasion of therapy." (PMID 25344858, 2014). "Gas6 secretion by exogenous sources in the surrounding tumor environment may explain this inconsistency." (PMID 25344858, 2014). "In addition, GAS6 expression was also higher in tumours from patients with residual disease compared to those without." (PMID 23878800, 2013). "Similarly, under the TNM-M scoring system, tumours from T4 patients (n = 7) tended to have higher GAS6 expression compared to T1 (n = 32), T2 (n = 21), and T3 (n = 107) patients (patients with smaller tumours) (P = 0.07163)." (PMID 23878800, 2013). "In clinical practice, the staining of a tumour biopsy for GAS6 may be useful for cancer prognosis assessment and/or for disease progression monitoring." (PMID 23878800, 2013).
tumor (continued). "In clinical practice, the staining of a tumour biopsy for GAS6 may be useful to assess cancer prognosis and/or to monitor disease progression." (PMID 23878800, 2013). "In addition, GAS6 expression level is higher in patients with greater tumour burden and/or with residual disease." (PMID 23878800, 2013). "In addition to TNM, the expression of several proteins involved in tumour genesis, particularly Gas6, and the number of infiltrating macrophages (CD68) were analysed." (PMID 21794149, 2011). "In contrast to the results obtained using western blotting, a weak expression of Gas6 mRNA in the same range as that of Gas6 mRNA in ccRCC tumor could be detected using quantitative real-time PCR (qRT-PCR)." (PMID 19888345, 2009). "Gas6 is a secreted protein shown to be involved in tumor cell proliferation and invasion." (PMID 19558675, 2009). "However, they may also promote tumor progression through GAS6-AXL and ANXA1-FPR1 signaling, interacting with fibroblasts, endothelial cells, and monocytes, while the role of MDK-SDC2 and MDK-(ITGA4+ITGB1) signals remains to be elucidated." (PMID 39776914, 2024). "Taken together, we showed that induction of the cell death resistance mechanism in tumor cells upon TMZ treatment is associated with transcriptomic changes in TME components, including inflammatory responses of Mg-TAMs and activation of the “eat-me” Gas6 pathway." (PMID 38566128, 2024). "Furthermore, growth-arrest specific 6 (GAS6) can induce tumor dormancy in cancer." (PMID 38464516, 2024). "Interestingly, a study revealed that stromal cells in the tumor microenvironment (TME) could continuously express GAS6 to activate the AXL receptor of adjacent tumor cells, thus promoting cancer drug resistance." (PMID 38045829, 2023). "Interestingly, Gas6 also has an essential function in the tumor microenvironment." (PMID 37265798, 2023). "We then found that both the tumor cells and the immune cells could express the ligand, GAS6, while only the dividing tumor cells displayed high expression of the receptor, TYRO3, which indicated the specific activation of the TYRO3 downstream signaling in those cells." (PMID 38110427, 2023). "Moreover, these mice remained completely tumor-free from day 21 after GAS6-CAR-T-cell treatment." (PMID 37475048, 2023). "Therefore, we examined the effects of GAS6-CAR-T cells on murine tumor cell lines." (PMID 37475048, 2023). "In addition, evidence suggests that the Gas6/AXL pathway is involved in tumor therapy resistance." (PMID 37265798, 2023). "Indeed, vimentin regulates the expression of the EMT-related transcription factors including Slug, which results in markedly elongated morphology of tumor cells and induces the expression of Axl, a receptor tyrosine kinase that is stimulated by the secreted protein growth arrest-specific 6 (Gas6)." (PMID 38313431, 2023). "Also, Gas6/TAM promotes migration of the tumor cells and, thus, metastasis." (PMID 35760058, 2022). "We could not find a significant association of any tumor or patient specific characteristics and expression of Gas6." (PMID 35760058, 2022). "Tumor-associated myeloid cells exhibited higher transcriptional expression of molecules linked to the “find me” (G2A), “eat me” (CD93, TIM1, SCARF1, SLC2A1, GAS6, TREM2, AXL, C1QA), and downstream processing (NR1H3, ATG7, PPARG, ABCA1, PPARD, DOCK180) phases of efferocytosis." (PMID 36439171, 2022). "While targeting the Gas6/Axl pathway has shown promising preclinical and clinical efficacy, targeting Gas6 or Axl as a monotherapy raises a concern about a possible narrow therapeutic index due to its expression and regulation of tumor growth in various cell types of the tumor." (PMID 34576116, 2021). "Furthermore, the unique tumor microenvironmental conditions may modulate Axl and Gas6 expression in both neoplastic and host cells to promote aggressive and pro-tumorigenic phenotypes." (PMID 32660000, 2020). "Local GAS6 concentrations in the tumor microenvironment (TME) may be higher." (PMID 32055714, 2020).
tumor (continued). "Importantly, Gas6 is involved in dissemination of tumor cells to the bone marrow." (PMID 32503267, 2020). "Importantly, activating AXL with GAS6 stimulated tumour sphere formation and stemness." (PMID 32051483, 2020). "Collectively, these results establish the 3‐gene (ENAH, AXL and GAS6) expression signature as a prognostic indicator, hallmark of an aggressive disease in PDAC and LUSC patients and strengthen the clinical relevance of the hMENA expression pattern analysis in both tumor cells and CAFs." (PMID 32909687, 2020). "In addition, studies using mouse models have shown that macrophage-derived Gas6 may have a tumor-promoting role in cancer progression." (PMID 32352034, 2020). "Herein we propose that the inhibition of the actin cytoskeleton regulatory protein hMENA may interrupt the communication between cancer cells and CAFs leading to an inhibition of tumor invasiveness by regulating GAS6/AXL axis and impacts PDAC and NSCLC patient prognosis." (PMID 32909687, 2020). "Similarly, 1.865 ± 0.999 ng/ml of Gas6 was detected in naïve mice sera (n = 48, lower-black), increased to 33.534 ± 6.738 ng/ml in tumor-bearing mice sera (n = 48, p < 1 × 10−6, lower-red), remained high at 35.505 ± 4.378 in the vehicle-treated mice sera (n = 12, p < 1 × 10−6, lower-green)." (PMID 31844158, 2019). "In addition, a low number of NK cells together with a high number of tumor associated macrophages (TAMs) has been correlated with poor survival in TNBC, possibly due to the inhibitory effect of TAM-derived growth arrest-specific protein 6 (Gas6) on the anti-metastatic NK cell activity." (PMID 31475003, 2019). "However, we have shown that the concentrations of AXL and GAS6 in plasma were not correlated with the corresponding expression levels in tumor tissue of NSCLC patients harboring EGFR activating mutations." (PMID 31419057, 2019). "Moreover, high Axl expression as well as high sAxl levels independently correlate with poor HCC patient survival, indicating that Gas6/Axl expression associates with a tumor-promoting rather than a tumor-suppressive signaling." (PMID 30567378, 2018). "All of these findings suggest that targeting Gas6 may be an effective approach to treating tumours." (PMID 29386018, 2018). "In the subgroup of patients with NSCLC with brain metastases, the high expression of AXL (AXLHigh) was significantly associated with GAS6 expression (P < 0.001), but not with tumor differentiation, gender, age, smoking history, pathology, T stage, N stage, CEA, and LDH (all P > 0.05)." (PMID 28551766, 2017). "Based on our results, we hypothesize that tumor cells, driven by autocrine GAS6, activate the TAM‐RSK‐dependent survival pathway during the initial steps of tumorigenesis and secondarily switch to a proliferation mode by activation of the MET and/or EGFR‐dependent SRC‐AKT pathway." (PMID 28675785, 2017). "Our results reveal that AXL–GAS6 signal axis potentially has a key role in NSCLC tumor progression and survival prognosis; and AXL alone or in combination with GAS6 may serve as feasible biomarker for prognostic prediction in patients with metastatic NSCLC to the brain." (PMID 28551766, 2017). "Furthermore, patients with tumors expressing tumor Axl and stromal Gas6 had poorer survival." (PMID 28878389, 2017). "Gas-6/Axl and NF-κB may be interesting targets for therapeutic intervention, since NF-κB promotes cancer resistance to apoptosis and production of growth factors in the stroma, which stimulates tumour progression." (PMID 28381274, 2017). "In addition to hypoxia, nutrient deprivation within the tumor microenvironment may also contribute to the activation of GAS6/AXL signaling." (PMID 27834845, 2016). "Gas6 correlated positively with a number of favourable prognostic variables including lymph node negativity (P=0.0002), younger age at diagnosis (P=0.04), smaller size of tumours (P=0.02), low Nottingham prognostic index scores (P=0.03) and low nuclear morphology (P=0.03)." (PMID 18283315, 2008).
tumor (continued). "Discussions on signalling pathways have revealed specific mechanisms underlying the bidirectional regulatory effects of the TAM receptor family on tumours, of which PI3K/Akt and Gas6/AXL are two particularly critical signals." (PMID 40088262, 2025). "As a result, our findings reveal a novel regulatory feedback loop involving eEF2K, MCP-1, and Gas6 in PDAC tumors, which promotes the accumulation of M2-TAMs and enhances tumor aggressiveness." (PMID 40624025, 2025). "Research has demonstrated that the Gas6/AXL signalling pathway plays a crucial role in promoting the survival, proliferation, mobility, and invasion of tumour cells." (PMID 40088262, 2025). "Chronic P.g. infection increases IL-6 secretion via TLR signaling, which activates STAT1 and STAT3, driving tumor progression through a feedback loop involving CXCL10, PD-L1, and GAS6 genes." (PMID 40924302, 2025). "Meanwhile, CAFs are found to secrete PROS1 and GAS6, which can activate AXL receptors on the surface of tumor epithelium cells, promoting immune suppression and tumor progression in ACPs." (PMID 40299526, 2025). "AXL in GAS6 - AXL ligand-receptor pairs, implicated in HGSOC drug resistance, was exclusively expressed in HLA TAM1 and HLA TAM2, and only monocytes could communicate with tumor cells through ANXA1–FPR, which serve as effective mediators in controlling inflammatory responses." (PMID 40036264, 2025). "This metabolic reprogramming enables GAS6 + macrophages to interact with TEAD3 + melanoma cells via the GAS6-TYRO3 ligand-receptor axis, promoting tumor proliferation, EMT, and metastasis." (PMID 41034991, 2025). "Examination of individual TAM receptor‐mediated signaling pathways revealed that the GAS6‐AXL pathway was prevalent in both normal and tumor tissues, albeit with distinct intercellular communication patterns." (PMID 40433916, 2025). "Its activation, primarily through binding of the ligand growth arrest-specific 6 (Gas6), triggers downstream signaling pathways including PI3K/AKT, MAPK, and NF-κB, which collectively contribute to tumor aggressiveness and poor clinical outcomes." (PMID 41011010, 2025). "We identified CCL8 as a critical mediator of the GAS6/AXL/MERTK pathway, primarily by inhibiting Treg infiltration into the tumor." (PMID 39774471, 2025). "Growth arrest-specific 6 (GAS6), a receptor tyrosine kinase AXL ligand, has been identified as a potential target against EOC for its diverse role in tumor progression." (PMID 40813689, 2025). "20G7-D9, an antibody against Axl, reduced Gas6-induced Akt activation, EMT marker expression, and tumor growth in pancreatic and breast cancer xenografts." (PMID 41011010, 2025). "To further explore whether GAS6-induced MMA accumulation contributes to immunosuppression—a key rationale for targeting this pathway—we collected conditioned medium (CM) from four treatment groups of TEAD3 + tumor cells and co-cultured it with primary murine CD8+ T cells." (PMID 41034991, 2025). "GAS6/AXL is active also between START and tumor-enriched C25fibro (the major CAF subtype in EGFR-mutant ADCs) until treatment with Unesbulin stops it completely." (PMID 38546390, 2024). "Along with its high-affinity ligand, the growth arrest-specific protein 6 (GAS6), AXL promotes tumour proliferation, survival, angiogenesis and invasion." (PMID 38539542, 2024). "In this paracrine loop, AML cells induce GAS6 expression in BMSC, which in turn increases AXL activation and tumor cell survival." (PMID 39367387, 2024). "Fortunately, the receptor molecules Axl/Gas6 and integrin αvβ5, proposed for Zika viruses, are particularly exposed on GBM tumor cells, which makes ZIKV envelopes perfect candidates for the encapsulation of retroviral vectors." (PMID 38398205, 2024). "Less is known about the control of GAS6 and PROS1 although both have been observed in the tumor microenvironment released from both tumor cells and infiltrating immune cells." (PMID 38906855, 2024).
tumor (continued). "The GAS6/AXL pathway influences drug resistance through interactions with other signals and regulation of the tumor microenvironment (TME)." (PMID 38539161, 2024). "With regard to GBM, however, it is important that the two potential ZIKV receptor candidates, Axl/Gas6 and integrin αvβ5, can be found regularly on GBM tumor cells." (PMID 38398205, 2024). "GAS6, an AXL ligand expressed under serous fasting states resulting in tumor cell growth arrest, is involved in tumor metastasis and infiltration." (PMID 38289361, 2024). "The Gas6/TAM family is involved in the modulation of inflammation, lipid metabolism, fibrosis, tumor progression and metastasis, processes which play an important role in the pathophysiology of acute and chronic liver diseases." (PMID 38298195, 2024). "Eric Ubil initiated a macrophage study and determined that tumor cells express MERTK ligands, GAS6, and Protein S, providing a source of tumor microenvironment (TME) ligand." (PMID 39062902, 2024). "The binding of Gas6 to TAM receptors (Tyro3, Mer, and Axl) regulates tumor cell proliferation, migration, and invasion." (PMID 39451556, 2024). "An important aspect of the TME is that it is a source of growth arrest-specific 6 (GAS6), which is the ligand of the AXL kinase and can provide another distinct transactivation pathway for HER family kinases expressed on tumor cells." (PMID 38892166, 2024). "After chemotherapy, neutrophils are recruited via tumor cell-secreted CXCL1 and CXCL2 signaling to the liver, where chemotherapy increases the expression of growth arrest specific 6 (Gas6) in circulating neutrophils." (PMID 38982491, 2024). "Ligands secreted by START, such as GAS6 and ICAM, lead to a protumoral phenotype acquisition (M2 phenotype) in the IMs, while CXCL2 and GRN, secreted by IMs, trigger tumor growth in START." (PMID 38546390, 2024). "These TANs express growth arrest specific 6 (Gas6), which leads to AXL receptor activation on tumor cells, enabling their regeneration." (PMID 38167055, 2024). "Once the cultures produced a sufficient amount of tumor cells, they were characterized for expression of ZIKV entry receptors Axl/Gas6 and Integrin αvβ5." (PMID 38398205, 2024). "AXL is a receptor tyrosine kinase that belongs to the TYRO3, AXL, and MERTK (TAM) family, which controls the tumor growth and EMT upon the binding of growth arrest-specific protein 6 (GAS6)." (PMID 39678497, 2024). "AXL (a member of the Tyro3-Axl-Mer/TAM family) is a receptor tyrosine kinase and is activated by binding to its ligand GAS6 (growth arrest specific 6); the GAS6/AXL pathway promotes tumor progression in part by facilitating immune evasion." (PMID 36588164, 2023). "Further, our results identified potential ligand-receptor pairs (MDK/LRP1, MDK/ALK, GAS6/MERTK, and GAS6/AXL) for cell communication between these two types of cells and tumor cells." (PMID 37733241, 2023). "Preclinical data demonstrated inhibition of Gas6-induced AXL and Src phosphorylation, tumor vessel density, tumor growth, and metastatic burden in renal cell carcinoma and ovarian cancer in response to treatment with AVB-500." (PMID 37469409, 2023). "Signaling pathways downstream Gas6/AXL signaling, including PI3K/AKT/mTOR, NF-κB, JAK/STAT3 and RAS/RAF/MEK/ERK, play critical roles in tumor cell cycle regulation, malignancy and drug resistance." (PMID 37265798, 2023). "Gas6/AXL signaling promotes immunosuppression and generates a pro-tumor microenvironment by altering and regulating the secretion of cytokines associated with immune cell function and movement." (PMID 37265798, 2023). "Hybrid cell expression of cell signaling pathways that mediate actin remodeling, cell migration and EMT, specifically GAS6-AXL (tumor-hybrid) and LGALS9-P4HB (hybrid-tumor), also align with increased migratory phenotypes of hybrid cells." (PMID 38106024, 2023).